CD22 (CD22 molecule)
Diseases named in the same sentence as CD22 in open-access papers (continued):
Sharing a sentence is not in itself a finding about the gene and the disease.
lymphoma (continued). "Based on our analysis, the most likely targets for clinical approval in disease groups such as lymphoma and multiple myeloma are CD20, CD22 (or in combination with CD19), CD38, BAFFR, CD7, and CD5." (PMID 40726984, 2025). "The primary targets for lymphoma and leukemia include CD19, CD123, CD22, CD33, and NKG2D ligands, while BCMA is the target for multiple myeloma." (PMID 40852706, 2025). "B-lymphoblastic leukemia/lymphoma is characteristically positive for B cell markers, including CD19, CD79a, and CD22, which can all be assessed by flow cytometric analysis." (PMID 40227608, 2025). "In our center, selected patients with lymphoma received sequential transfusions of anti-CD19 and anti-CD22 CAR-T cells when immunohistochemistry confirmed co-expression of both antigens." (PMID 41235228, 2025). "For lymphoma, molecules such as CD19, CD22, CD30, and CD79b are commonly targeted, highly expressed molecules." (PMID 40843358, 2025). "In a meta-analysis with a data cutoff in March 2022, a total of seven CD22-CAR T clinical trials with 149 patients had primary efficacy data, but only two enrolled patients with lymphoma." (PMID 38711850, 2024). "CAR-T cells equipped with anti- Siglec-2 (CD22) and anti- Siglec-3 (CD33) receptors exert potent therapeutic effects on leukemia and lymphoma, respectively." (PMID 38254780, 2024). "The challenges of CD22-targeted therapy in B-NHL include the higher variability of CD22 expression on lymphoma cells than CD19 and CD20, down regulation of CD22 and low antigen density." (PMID 38711850, 2024). "Various lymphoma antigens are amenable to CAR-T cell targeting, such as CD19, CD20, CD22, CD30, the kappa light chain, and ROR1." (PMID 39206402, 2024). "CD22 and CD33, which are consistently expressed on leukemia and lymphoma cell surfaces, are potent antibody targets in hematological conditions." (PMID 38254780, 2024). "ATA B cells can decrease CD5 in middle age and increase CD11b++CD22++ in ZAP70–CD5–, generating old age leukemia/lymphoma with autoimmune disease and control Thy-1, also ZAP70+CD5+ with CD11b+CD22+." (PMID 38570827, 2024). "Of note, several genes reflecting B cells (CD20/MS4A1, CD19, CD22, CD79B) were significantly highly expressed in HLA‐I+ compared to HLA‐I− lymphomas, suggesting that the prognostically favorable B‐cell‐rich TME is a feature of HLA‐I+ HL." (PMID 38836098, 2024). "As a result, therapies, such as CD22/SIGLEC2 CAR-T and CD33/SIGLEC3 CAR-T, have been introduced to address refractory leukemia or lymphoma." (PMID 39697338, 2024). "One approach to address this problem is to use dual-targeting CAR T cells, as observed in clinical trials using CAR T cells targeting CD19/CD22 for leukemia and lymphoma, CD19/CD20 for lymphoma, and BCMA/CD38 for MM11–15." (PMID 38643278, 2024). "Anti-CD22-(LC:K149C)-SN36248 yielded a longer response duration than pinatuzumab vedotin and showed anti-lymphoma effects in several mouse models, including two resistant to pinatuzumab vedotin (Raji and WUS-DLCL2)." (PMID 37821931, 2023). "DT2219, a bispecific ligand-directed toxin targeting both CD22 and CD19, is conjugated to the catalytic domain of diphtheria toxin and is used for treating refractory or relapsed B-lineage leukemia or lymphoma." (PMID 36882399, 2023). "CD22-targeted and bispecific CARs, such as CD19-CD22 and CD20-CD22 CARs, are the ongoing trials in the treatment of lymphoma and leukemia." (PMID 36882399, 2023). "In this study, we assessed a total of 131 patients with different B-cell CLDs, including B-CLL, atypical B-CLL, MCL, and CD5-/CD10-lymphoma, for a panel of B-cell-specific markers viz CD5, CD20, CD22, CD23, and FMC-7." (PMID 36624655, 2023). "One strategy to improve efficacy is finding novel targets and designing constructs targeting more than one antigen, such as the dual-targeting CD19/CD22 CAR in B-cell malignancies, dual CD19/CD20 CAR in lymphomas and leukemia, and CD19/BCMA-specific CAR in MM." (PMID 36362130, 2022).
lymphoma (continued). "CD22-directed CAR-T cells have shown efficacy against leukemia and lymphoma, representing the first alternative CAR target with comparable efficacy to CD19 CAR-T." (PMID 36362130, 2022). "We focused on highly expressed antigens found in primary leukemia and lymphomas, such as CD19, CD20, CD22, ROR-1, CD276, CD79B, and CD10." (PMID 36289682, 2022). "Currently, six CAR-NK therapies (CD19-CAR NK, CD22-CAR NK, CD19/CD22, CD7-CAR NK,CD19-t-haNK) are assessed in clinical trials for the treatment of lymphoma patients." (PMID 33815422, 2021). "Siglec-2 (CD22) and Siglec-3 (CD33)-targeting antibody–drug conjugates have been approved by US Food and Drug Administration for the treatment of lymphoma and leukemia." (PMID 34112250, 2021). "Several CAR-NK cells (targeting CD19, CD22, CD7, and CD33) are currently in clinical trials for the treatment of certain types of leukemia or lymphoma (e.g., NCT03056339, NCT04004637)." (PMID 33505304, 2020). "Gupta and collaborators demonstrated a link between PTEN and PI3K pathway activation and the response of human lymphoma cell lines to hexavalent antibodies (HexAbs) (anti-CD20, anti-CD22 and anti-CD22-20)." (PMID 32727102, 2020). "Significantly, we also investigate the ability of these analogs to increase CD22 surface expression in in vitro models of ALL and AIDS-related lymphomas in connection with emerging antigen-targeted therapies." (PMID 32312992, 2020). "In leukemia and lymphoma, CD19, CD22, and CD20 have different expressional hierarchies in tumor cells." (PMID 31637014, 2019). "CD19, CD22, CD37, and CD40 have been identified, thanks to lymphoma molecular profiling, and are currently under investigation for the development of new antibody-based treatments." (PMID 30583481, 2018). "Flow cytometry revealed a different population of lymphoma cells, this time positive for CD5, CD19, CD20, and CD22, with dim expression of CD45 and CD38." (PMID 27957358, 2016). "All lymphoma cases were immunohistochemically stained for CD3 and CD22, markers of the T and B cells, respectively." (PMID 27146058, 2016). "CD22 has been identified as an ideal target for ADCs due to high expression on the surface of malignant B-lineage leukemia (>90% of B cell ALL) and lymphoma cells and rapid internalization after binding." (PMID 24795859, 2014). "Phase I clinical trials in humans with lymphoma and leukemia have demonstrated the anti-tumor efficacy of HD37-dgRTA either alone or in combination with an anti-CD22 IT." (PMID 22069716, 2011). "CD22 specificity was also confirmed using an alternate human lymphoma line, Raji or Raji-CD22-KO target cells, and with CD22-overexpressing K562 or wild-type (WT) K562 cells, which do not express CD22." (PMID 38596311, 2024). "When we examined expression data for additional ATCC parental cancer cell lines without already existing luciferase reporters, we found that the lymphoma cell lines Raji, Farage, and Daudi express high levels of CD19, as well as high levels of CD20, CD22, and CD38." (PMID 39061136, 2024). "Interestingly, the pattern of CD22, CD23, and FMC-7 antigens, along with the CD5 co-expression, permitted the accurate classification of all B-CLL, and CD5-/CD10-lymphoma using flow cytometry." (PMID 36624655, 2023). "Also, the potential benefits for combining CD19 and CD22 (as well as CD20) in antibody and CAR-T format has been demonstrated in lymphoma models." (PMID 37247022, 2023). "Among the anti-CD22 ADCs, inotuzumab ozogamicin (CMC-544) was approved by the FDA in August 2017 for R/R B cell ALL as monotherapy and it is also increasingly evaluated in preclinical and clinical trials against lymphoma." (PMID 36654819, 2022). "To further study the efficacy of CD22 CAR-T and sequential CD22/19 CAR-T therapy in vivo, we established a CD19 and CD22 both positive lymphoma xenograft mouse model by intravenously inoculating the lymphoma cell line Namalwa cells into NOD/SCID mice." (PMID 35317863, 2022).
lymphoma (continued). "ALL or lymphoma cell lines, Daudi, Namalwa, Nalm-6 and the CD22 negative control cell line K562, were cocultured with CD22 CAR-T cells at an E:T ratio of 1:1." (PMID 35317863, 2022). "We investigated the effects of six small molecule pharmacological agents, which interfere with endocytic and other processes, on SA-mediated augmentation of saporin and saporin-based immunotoxins (ITs) directed against CD7, CD19, CD22 and CD38 on human lymphoma and leukaemia cell lines." (PMID 30791598, 2019). "A number of new specific antibodies, including the anti-CD22, anti-CD40, anti-CD19, anti-CD19/CD3, and anti-CD37 antibodies, are currently used for alternative antibody-based therapy in lymphomas." (PMID 30583481, 2018). "Pioneering work was done with chemically linked immunotoxins by the group of Stirpe in Bologna and Flavell in Southampton, directing Saporin to human leukemia and lymphoma cells expressing differentiation antigens such as CD2, CD7, CD19 and CD22 on their plasma membrane surface." (PMID 29438358, 2018). "These lymphomas are typically positive for pan-B cell markers, such as CD19, CD20 and CD22." (PMID 29610634, 2017). "The lymphoma was CD45-negative and weakly CD22- and CD30-positive." (PMID 23880011, 2013). "In lymphoma, MAb targeting CD20 or CD22 are available and could be used for immuno-PET purposes and the feasibility of immuno-PET using anti-CD20 MAb has been demonstrated." (PMID 22899920, 2012). "Because CD22 is upregulated on B-cell lymphomas, this higher level of expression allows the T cells with the TCR recognising the membrane-distal epitope on CD22 to lyse lymphoma cells, while sparing normal B cells." (PMID 20432238, 2010). "However, CD22-targeting antibodies like Epratuzumab have been tested in clinical trials [NCT0030182, NCT01262365, NCT01261793], which proved to be safe and well-tolerated in lymphoma as well as lupus patients." (PMID 41154421, 2025). "Anti-CD22 immunotherapeutic agent Inotuzumab may lead to decreased or absent CD22 expression in B-lymphoblastic leukemia/lymphoma blasts at the time of relapse." (PMID 40227608, 2025). "Probably this dosage limitation may underlie the observation that PE38-based immunotoxins targeting different surface markers or receptors expressed in lymphoma cells (e.g. CD22 or CD25) could not induce either partial or complete remissions in non-Hodgkin lymphoma patients 41,42." (PMID 32373205, 2020). "We further checked IS7 specificity for CD22 using a lymphoma cell line, BL41, with CD22 knocked out and detected no signal when stained with IS7 antibody." (PMID 37269947, 2023). "Our results indicated that the expression pattern of CD22, CD23, FMC-7, and CD5 allowed us to accurately and differentially diagnose the B-CLL, MCL, and CD5-/CD10- lymphoma, while it was not capable of differentiating MCL from atypical CLL." (PMID 36624655, 2023). "In general, CD19CAR T cells become non-functional in CD19 negative lymphoma subsets; however, AdCAR T cells can be redirected to alternative target antigens beyond CD19, such as CD20, CD22, CD79B, and ROR-1." (PMID 36289682, 2022). "While for the other 4 cases whose BM involvement was diagnosed by flow cytometry, their lymphoma cells were positive for CD20, CD22, CD79b, and the surface light chain, while negative for CD138." (PMID 34503477, 2021). "The lymphoma cells usually express CD45 without expression of pan-B markers (CD19, CD20, CD22 and CD79a) or T/NK cell markers." (PMID 25613729, 2015). "In patients treated with an agent targeting CD22, CD24 may serve to identify normal and neoplastic B cells; however, not all cases of B-lymphoblastic leukemia/lymphoma are CD24 positive, so analysis for additional B cell markers, such as CD79a, may be helpful." (PMID 40227608, 2025). "They found that CD22, CD23, FMC-7, and CD5 expression could be used to diagnose CLL, MCL, and CD5−/CD10− lymphoma but could not differentiate MCL from atypical CLL." (PMID 37760396, 2023).
acute lymphoblastic leukemia (108 papers, 2006 to 2026). Leukemia with an acute onset, characterized by the presence of lymphoblasts in the bone marrow and the peripheral blood. "While CD22 is commonly associated with acute lymphoblastic leukemia, it is also present in various other hematological disorders like CLL, especially in atypical forms of CLL." (PMID 39329950, 2024). "Combined loss of both CD19 and CD22 antigens was validated in samples from pediatric and young adult patients with B cell acute lymphoblastic leukemia (B-ALL) that relapsed after CD19 CAR-T–targeted therapy." (PMID 38376944, 2024). "We previously reported a splicing defect associated with the deletion of CD22 Exon 12 (CD22E12) in leukemia cells from patients with CD19+ B-precursor acute lymphoblastic leukemia (B-ALL)." (PMID 36900389, 2023). "Antibody–drug conjugates (ADCs) have long been pursued to improve cure rates in these malignancies, with a major focus on CD33 (for acute myeloid leukemia [AML]) and CD22 (for B-acute lymphoblastic leukemia [B-ALL])." (PMID 41514580, 2025). "Sequential CD19 and CD22 chimeric antigen receptor (CAR)-T cell therapy offers a promising approach to antigen-loss relapse in relapsed/refractory (R/R) B-cell acute lymphoblastic leukemia (B-ALL); however, research in adults remains limited." (PMID 39754190, 2025). "Acute lymphoblastic leukemia cells resistant to CD19 immunotherapies exhibit combined loss of CD19 and CD22 and an enhanced sensitivity to BTK and MEK inhibition." (PMID 38376944, 2024). "InO plays a crucial role in the treatment of acute lymphoblastic leukemia (ALL) by targeting cancer cells that abnormally express CD22, thereby inducing cell cycle arrest and apoptosis." (PMID 38519953, 2024). "The IS7-CAR has superior avidity and is active and specific against CD22-positive targets, including B-acute lymphoblastic leukemia patient-derived xenograft samples." (PMID 37269947, 2023). "We previously reported a splicing defect (CD22ΔE12) associated with the deletion of exon 12 of the inhibitory co-receptor CD22 (Siglec-2) in leukemia cells from patients with CD19+ B-precursor acute lymphoblastic leukemia (B-ALL)." (PMID 36900389, 2023). "It targets CD22, an antigen expressed on relapsed/refractory B-cell precursors in acute lymphoblastic leukemia (ALL)." (PMID 37790810, 2023). "Pan announced that CD22 CAR-T cell therapy was used in patients with refractory or relapsed B acute lymphoblastic leukemia, and the patients only suffered mild cytokine release syndrome and neurotoxicity related to CAR-T cell therapy." (PMID 37817249, 2023). "T cell immunotherapies, notably chimeric-antigen receptor T (CAR-T) cells against CD19 or CD22 on acute lymphoblastic leukaemia (ALL) blasts, have demonstrated the potential to generate clinically significant immune responses in haematological malignancies." (PMID 35962843, 2023). "Motivated by the success of Mylotarg, a similar immunoconjugate targeting CD22, Inotuzumab ozogamicin, was recently approved as monotherapy for adults with r/r B-cell precursor CD22-positive acute lymphoblastic leukemia (ALL)." (PMID 34827170, 2021). "The modulation of CD22 in mouse models by an α2,6-sialylated glycan or an anti-CD22 antibody conjugated to an immunotoxin has been tested to eliminate B cells in cases of acute lymphoblastic leukemia." (PMID 33810246, 2021). "We present a case of a 20-year-old male patient with acute lymphoblastic leukemia developed CRS after CD19/CD22 bispecific CAR-T treatment." (PMID 34106613, 2021). "The subjects of the trial were affected with childhood R/R CD22+ acute lymphoblastic leukemia (age range ≥1 to ≤18 years)." (PMID 34575992, 2021). "The FDA has just approved inotuzumab ozogamicin (Besponsa®) (Pfizer Inc. and UCB S.A.)anti-CD22 ADC therapy in patients with acute lymphoblastic leukemia, which combines the epratuzumab anti-CD22 mAb with the cytotoxic antitumor antibiotic calicheamicin." (PMID 33333862, 2020).
acute lymphoblastic leukemia (continued). "Inotuzumab ozogamicin (IO) is an anti-CD22 calicheamicin immunoconjugate that has been recently approved for the treatment of relapsed or refractory B-Acute Lymphoblastic Leukemia (r/r B-ALL)." (PMID 30834235, 2019). "Several studies have reported encouraging results from the application of dual CAR-T cells that target both CD19 and CD22 to treat patients with acute lymphoblastic leukemia (ALL), reporting that this therapy is more effective than CD19 CAR-T cell therapy alone." (PMID 39850899, 2024). "Inotuzumab ozogamicin is a CD22-directed monoclonal antibody conjugated to calicheamicin, which has been approved by the Food and Drug Administration for adults and pediatric patients 1 year and older with relapsed or refractory CD22-positive B-cell precursor acute lymphoblastic leukemia." (PMID 39449299, 2024). "To date, the clinical application that has determined the success of CAR T cells has been conducted mainly targeting the CD19 and CD22 molecules in B cell-Acute Lymphoblastic Leukemia (B-ALL) and B cell lymphoma and against B-Cell Maturation Antigen (BCMA) for multiple myeloma." (PMID 35757746, 2022). "The biological reason for the development of VOD are still unknown, however similar observations come from patients treated with inotuzumab-ozogamicin, an anti-CD22 calicheamicin conjugate, used for the treatment of acute lymphoblastic leukemia (ALL) patients." (PMID 34572794, 2021). "The application of daratumumab for the eradication of MRD in high-risk advanced relapse of T-cell or CD19/CD22-negative acute lymphoblastic leukemia has been demonstrated." (PMID 33292550, 2020). "An investigation on adult acute lymphoid leukemia patients confirmed abundance of CD22 expression." (PMID 29642542, 2018). "Antigen escape relapse is a major challenge in targeted immunotherapies, including CD19- and CD22-directed chimeric antigen receptor (CAR) T-cell for B-cell acute lymphoblastic leukemia (B-ALL)." (PMID 40268897, 2025). "Inotuzumab has shown remarkable efficacy in CD22-positive relapsed/refractory adult and pediatric acute lymphoblastic leukemia (ALL) and is being investigated in the frontline setting in childhood ALL." (PMID 40606948, 2025). "For instance, a clinical trial involving CD19/CD22-CAR-T cells for refractory acute lymphoblastic leukemia (ALL) has highlighted the potential of dual CAR strategies." (PMID 40260240, 2025). "IO is a rescue therapy for patients with relapsed or refractory CD22-positive precursor B-cell acute lymphoblastic leukemia (R/R CD22-positive BCP-ALL)." (PMID 41144385, 2025). "CAR-T therapies targeting either CD19 or CD22 have shown significant promise for treating relapsed or refractory B-lineage acute lymphoblastic leukemia (r/r B-ALL)." (PMID 40719826, 2025). "A recent meta-analysis of CD22 CAR-T clinical trials for relapsed B cell acute lymphoblastic leukemia (B-ALL) found a mean complete response rate of 75%, and this was raised to 87% when combined with CD19-targeted CAR." (PMID 38596311, 2024). "The efficacy of CD22 or CD19 chimeric antigen receptor T (CAR‐T) cells in the management of acute lymphoblastic leukemia (ALL) and non‐Hodgkin lymphoma (NHL) was observed." (PMID 37667978, 2023). "In recent years, chimeric antigen receptor (CAR) T‐cell therapy targeting CD19 or CD22 antigen has been used as a potent approach to treat refractory/relapsed (r/r) B‐cell acute lymphoblastic leukemia (B‐ALL) and achieved remarkable efficacy." (PMID 35995579, 2022). "Further clinical study of CD22/CD19 CAR-T sequential therapy was conducted in 4 R/R adult B-cell acute lymphoblastic leukemia (B-ALL) patients." (PMID 35317863, 2022). "Chimeric antigen receptor (CAR) T cells targeting CD19 or CD22 have shown remarkable activity in B cell acute lymphoblastic leukemia (B-ALL)." (PMID 34642489, 2021).